IL6 (interleukin 6)
Diseases named in the same sentence as IL6 in open-access papers (continued):
Sharing a sentence is not in itself a finding about the gene and the disease.
tumor (continued). "Tumor-secreted IL-6 and GM-CSF are known drivers of MDSC expansion, and the ability of PLX51107 to inhibit their production could contribute to the reduced frequency of MDSCs." (PMID 40762981, 2025). "IL-6 serum concentrations were found to increase as tumor stage progressed." (PMID 40317079, 2025). "In cancer patients, the tumor microenvironment triggers a persistent systemic inflammatory response characterized by elevated cytokines such as IL-6, TNF-α, and IL-1β, which can impair renal vascular tone and lead to renal hypoperfusion and structural kidney damage over time." (PMID 40722492, 2025). "Moreover, AHR-high expression was associated with inflammatory response, IL-2 and IL-6 signalling, and tumour necrosis factor alpha (TNF-α) signalling via NF-κB in both ER+ and ER- tumours." (PMID 40646277, 2025). "For example, F. nucleatum has been shown to inhibit NK- and T-cell activation through Fap2–TIGIT interactions, while P. gingivalis promotes tumor growth by inducing myeloid-derived suppressor cells through the secretion of IL-6 and IL-8 from oral keratinocytes." (PMID 41225628, 2025). "An inverse relationship between miR-26 levels and IL-6 has been observed in some tumor cells, suggesting that miR-26 may regulate inflammation and tumorigenicity by down-regulating IL-6." (PMID 40129920, 2025). "In this review, we summarize the role of IL6 in inflammation and how IL6 contributes to ovarian tumorigenesis within the tumor microenvironment, influencing whether the tumor is subsequently classified as “hot” or “cold”." (PMID 40427188, 2025). "Exosome‐mediated IL‐6 secretion by NPC cells facilitates tumor progression." (PMID 41316520, 2025). "Thus, data regarding the key cytokine IL-6 suggests a link between the role of hypoxia in tumor progression and the mechanisms used by hypoxia in the progression of inflammation and autoimmunity." (PMID 40963621, 2025). "Moreover, SEC61G reshaped the tumor immune microenvironment by promoting microglial M2 polarization and suppressing M1 polarization, accompanied by increased secretion of IL-6 and IL-10." (PMID 39990664, 2025). "When reimplanted in vivo, targeting individual PTIS proteins such as IL-6 could slow PTR tumor growth but broader PTIS inhibition via type I IFN signaling disruption provided a more potent anti-tumor effect." (PMID 39663510, 2025). "Although IL-6 may support tumor progression in chronic settings, its acute elevation reflects early T-cell activation and inflammatory responses." (PMID 40722845, 2025). "Tumor volumes were slightly lower in the treated group (Online Resource 2a) and, most importantly, survival of treated animals was somewhat higher than controls (Online Resource 2b), suggesting IL-6 inhibition and impairment of DS-1 cell proliferation." (PMID 38980514, 2025). "Additionally, IL-6 secreted by tumor-resident senescent stromal cells can enhance MDSC infiltration and decrease the efficacy of anti-tumor T cell responses." (PMID 39897036, 2025). "Additional immunosuppressive factors within the TME, including indoleamine 2,3-dioxygenase (IDO) and interleukin-6 (IL-6), recruit myeloid cells and promote lymphocyte differentiation into regulatory T cells (Tregs), leading to dampened anti-tumor T-cell responses." (PMID 40427130, 2025). "This indicates that the primary IL-6 producers in the ESCC tumor microenvironment are CAFs." (PMID 40433391, 2025). "Pro-inflammatory cytokines within the tumor microenvironment, such as IL-6 and TNF-α, may stimulate MUC16 transcription via JAK/STAT and NF-κB signaling pathways." (PMID 40422614, 2025). "Interestingly, upon MSN upregulation in tumor cells, there was an increase in phosphorylated NF-κB (p-NF-κB) under IL-6 treatment." (PMID 40696387, 2025). "Furthermore, IL-6 promotes the differentiation and expansion of Tregs, thereby exacerbating the immunosuppressive conditions present in the tumor microenvironment." (PMID 41394878, 2025).
tumor (continued). "In GC, IL-6 plays a dual role in tumor progression and in the modulation of the immune system." (PMID 41376630, 2025). "In cancer, IL-1β, IL-4 and IL-6 are well-known for their tumor promoting effects, including enhancing tumor cell proliferation and survival, supporting cancer cell stemness, and facilitating invasion and angiogenesis through autocrine signaling or crosstalk with tumor infiltrating immune cells." (PMID 40108668, 2025). "For instance, IL-6 overexpression may signify both tumor progression and systemic inflammation, complicating its interpretation as a biomarker." (PMID 40881677, 2025). "Moreover, components of the tumor’s exosomes, such as IL-6, can participate in the reduction of maturation of T cells." (PMID 39561105, 2025). "This immune reprogramming can be mediated through sustained exposure to tumor-derived cytokines such as IL6 (interleukin-6), TNFα (tumor necrosis factor-alpha), IL1β (interleukin-1 beta), TGFB (transforming growth factor beta), chemokines, growth factors, and extracellular vesicles." (PMID 41514627, 2025). "In this context, PDE7 inhibition with concomitant treatment with PTX increased the release of IL-6, which may have contributed to changes in mitochondrial morphology and, consequently, the metabolism of tumor cells." (PMID 40535773, 2025). "In terms of inflammatory factors, IL6, IL1B, and NFKB1 expression levels were notably reduced in the combination treatment group relative to the control group, suggesting a potential reduction in tumor-associated inflammation." (PMID 40361560, 2025). "Polarized M2 macrophages subsequently release VEGF and IL-6, which supports tumor progression." (PMID 39814702, 2025). "This relationship highlights the relevance of STAT3 and IL-6 as potential therapeutic targets, suggesting that strategies aimed at modulating this pathway could be promising for combating tumor progression." (PMID 40733498, 2025). "MKC8866 is a salicylaldehyde analogue that has been proven to inhibit the activity of IRE1α to reduce the secretion of various tumor‐promoting factors, including IL‐6, IL‐8, chemokine ligand 1 (CXCL1), transforming growth factor β2 (TGFβ2), and GM‐CSF, to inhibit breast cancer cell proliferation." (PMID 40547943, 2025). "When comparing mice treated with the TGFβ vaccine to those receiving the vaccine alongside an anti-IL-6R antibody, we found that inhibition of IL-6 signaling reduced overall T-cell infiltration within the tumor, including decreases in CD4+ T cells, CD8+ T cells and regulatory T cells." (PMID 39653766, 2025). "Notably, both selumetinib and MSU-42011, alone and in combination, reduced Il-6 mRNA expression by 52.76% (p = 0.0007), 63.12% (p < 0.0001), and 54.26% (p = 0.0005) compared with vehicle treatment, as measured in tumor lysates." (PMID 40563570, 2025). "Cancer-associated fibroblasts (CAFs) in the tumor microenvironment are implicated in chemoresistance, but their role in L-OHP resistance via interleukin-6 (IL-6) secretion remains unclear." (PMID 40718440, 2025). "As an additional perspective for future research, it is important to highlight that in preclinical studies, the administration of tocilizumab, a monoclonal antibody inhibitor of IL-6, has demonstrated a significant delay in tumor progression compared to control groups." (PMID 40558287, 2025). "IL-6, a pro-inflammatory cytokine elevated in response to SDIRs, reinforces immune suppression and enhances angiogenesis, amplifying the niche’s capacity to sustain disseminated tumor cells." (PMID 40649918, 2025). "In vivo, KL tumours showed higher IL‐6 expression than K tumours, especially in males." (PMID 40702652, 2025). "IL6 can stimulate cancer cell proliferation and survival and promote the recruitment and activation of myeloid cells that further suppress antitumor immunity and facilitate tumor growth." (PMID 40650134, 2025).
tumor (continued). "RETA induced immune reprogramming systemically and in the tumor microenvironment with durable anti-tumor immunity evidenced by elevated circulating IL-6, increased antigen presenting cells, reduced immunosuppressive cells, and activation of pro-inflammatory pathways." (PMID 40094000, 2025). "Tumors from RSV-treated mice showed increased miR-34c and decreased KITLG expression, accompanied by reduced IL-6 levels, suggesting that RSV may disrupt IL-6-driven tumor progression." (PMID 40969596, 2025). "Together, these findings indicate blocked autophagic clearance in the IL6 tumor-bearing mice." (PMID 41256541, 2025). "Additionally, IL-17 significantly enhances tumor angiogenesis by upregulating the expression of pro-angiogenic factors such as vascular endothelial growth factor (VEGF), IL-6, and IL-8, which provide crucial nutritional support for tumor growth." (PMID 40370457, 2025). "Notably, this study also observed a decrease in resting mast cells, which can actively eliminate tumor cells and prevent tumorigenesis through cytokines, such as IL-1, IL-4, IL-6, and TNF-α." (PMID 40755754, 2025). "Furthermore, polysaccharides reduce pro-inflammatory cytokines, including TNF-α and IL-6, which are critical contributors to the tumor-promoting microenvironment." (PMID 39852004, 2025). "These CAF–tumor interactions are now targeted therapeutically: agents against fibroblast activation protein (FAP) on CAFs (e.g., FAP-specific CAR-T cells or inhibitors) and inhibitors of CAF-derived signals (e.g., TGF-β or IL-6 blockade) are being explored to disrupt the tumor-supportive stroma." (PMID 41409250, 2025). "In summary, the observations of this study showed that the combination of FZLZD and XELOX plus sintilimab in the treatment of advanced GC can significantly reduce TCM syndrome scores, reduce serum tumor marker levels and IL6 expression, and enhance the therapeutic effect of advanced GC." (PMID 40958249, 2025). "IL-6 promotes tumor growth and M2 polarization by enhancing immunosuppressive traits." (PMID 40563651, 2025). "The TME in CRC is often characterized by chronic inflammation, where inflammatory mediators such as cytokines (e.g., TNF-α, IL-6), chemokines, and immune cells (e.g., macrophages) contribute to tumor progression and metastasis through activation of key signaling pathways, including PI3K/AKT." (PMID 41179295, 2025). "M1 macrophages are typically activated by inflammatory cytokines (e.g., GM-CSF, TNF-α, IFN-γ, LPS) and are characterized by their secretion of proinflammatory cytokines (e.g., IL-1α/β, IL-6, IL-12, IL-23), which enhance cytotoxic immune responses and anti-tumor immunity." (PMID 40079009, 2025). "While activated M1 cells produce proinflammatory cytokines such as IL-1, IL-6, and TNFα, stimulated M2 TAMs may contribute to tumor angiogenesis along with other TME cells by releasing VEGF." (PMID 40607405, 2025). "Moreover, by producing IL-1β and IL-6, myeloid cells can polarize additional macrophages and neutrophils toward tumor-promoting phenotypes, further reinforcing immunosuppression within the TME." (PMID 40821795, 2025). "Additionally, we will discuss the complex mechanisms by which IL6 affects tumor growth, metastasis, and therapy resistance." (PMID 40427188, 2025). "A study on lung cancer revealed that TAMs promote the migration and invasion of tumor cells through the secretion of cytokines such as IL-6 and IL-8 and simultaneously increase the resistance of tumor cells to EGFR inhibitors, reducing the efficacy of chemotherapeutic drugs." (PMID 40850976, 2025). "Remarkably, CPD-L1 plus AZA combination therapy could significantly upregulate the levels of IFN-γ, IL-12p70, TNF-α, and downregulate the levels of IL-6, IL-10 in tumor tissues." (PMID 40994623, 2025).
tumor (continued). "For instance, fibroblasts with tumor-associated characteristics have been shown to suppress the functionality of CD8+ T-cells through the induction of an IL-6 autocrine signaling loop and by engaging with Th17 cells, thereby modulating the tumor microenvironment." (PMID 40485724, 2025). "Notably, TNF-α exhibits cytotoxic effects on tumor cells and also stimulates the secretion of IL-1β and IL-6." (PMID 40559782, 2025). "Moreover, lactate stimulates CAFs to secrete IL-6, thereby fostering an immunosuppressive microenvironment that facilitates tumor progression." (PMID 41152975, 2025). "While IL-6 can have pro-tumor effects, it also has a role in modulating anti-tumor immunity." (PMID 40573301, 2025). "Additionally, pro-inflammatory cytokines such as TNF-α and IL-6 can exacerbate tumor progression by promoting chronic inflammation, further hindering the efficacy of immunotherapies." (PMID 40109332, 2025). "Similarly, in PDAC, upregulation of circCUL2 in NFs induces the transition to inflammatory CAF phenotype, which promotes tumor development through IL‐6 secretion by regulating the miR‐203a‐3p/MyD88/NF‐κB/IL‐6 axis." (PMID 39901896, 2025). "Chronic inflammation may initiate and promote carcinogenesis through proinflammatory cytokines (e.g., IL-6) and reactive oxygen species, which activate transcription factors driving tumor growth." (PMID 40642165, 2025). "Furthermore, expression analysis based on scRNA data revealed that IL-6 is predominantly expressed by fibroblasts, tumour cells, and macrophages, while IL-6R and IL6ST are mainly expressed in tumour cells, CAFs, and various immune cells." (PMID 39858048, 2025). "Liposomal IL-4, IL-6, and IL-21 therapies show potential across various tumor types." (PMID 40143046, 2025). "From these results, we hypothesized that patients with high serum IL-6 levels are more likely to have a TAM-rich tumor microenvironment." (PMID 39652104, 2025). "This suggests that IL-6 is a key mediator linking tumor and host to gut microbial changes." (PMID 40572244, 2025). "In addition, TNF-α can stimulate the production of IL-6 and IL-8, and IL-6 can be self-induced in tumor cells, which in turn promotes the growth of tumor cells." (PMID 41154714, 2025). "Inflammatory and immune components also play a key role: IL-6 mediates chronic inflammation and may promote tumor progression and treatment resistance, while CRP levels indicate systemic inflammatory responses." (PMID 41244922, 2025). "One study has reported that it can reduce IL-10 and IL-6 levels, which may help limit tumor growth and spread." (PMID 40160316, 2025). "In certain contexts, SASP elements—particularly IL-1α, IL-6, and IL-8—promote the recruitment of M1-like macrophages, Th1 cells, and NK cells, facilitating the clearance of senescent tumor cells and suppressing tumor progression." (PMID 41181123, 2025). "Importantly, IL-6 induces strong immunosuppression in the tumor microenvironment by recruiting immunosuppressive cells and impairing T cell infiltration." (PMID 40255422, 2025). "Mgl2 KO tumors displayed significant enrichment of immune and inflammatory pathways, including TNF-α/NF-κB, IL-6/JAK-STAT3, interferon-α/γ, and IL-17 signaling—pathways broadly associated with myeloid activation, cytokine production, and tumor immunosurveillance 53,54." (PMID 41377951, 2025). "Patients with a poorer PS showed positive interactions among nodes that favored tumor growth, as they were closely correlated with the generation of a proinflammatory environment (IL6), a suppressive microenvironment (IL10), and resistance to immune checkpoints (PD-L2)." (PMID 40149259, 2025).
tumor (continued). "In addition, IL-6 supports hepatic glycogen breakdown to supply energy for tumor cells and encourages the growth of vascular endothelial cells, which plays a critical role in tumor angiogenesis." (PMID 41346580, 2025). "Tumor-driven cytokines, particularly interleukin-6 (IL-6), may disrupt normal erythropoiesis and contribute to alterations in MCV and MCH levels." (PMID 40299490, 2025). "However, inflammation-induced disruption of the BBB - mediated by TANs and cytokines (e.g. IL-1β, TNF-α, and IL-6) - can increase vascular permeability and create a permissive environment for tumor cell infiltration into the CNS." (PMID 40496607, 2025). "The tumor's presence can elicit an inflammatory response, promoting elevated levels of interleukin-6 (IL-6), C-reactive protein, immunoglobulins, and erythrocyte sedimentation rate, contributing to systemic symptoms such as fever, malaise, anorexia, and weight loss." (PMID 40842978, 2025). "Moreover, IL6 plays a crucial role in maintaining energy metabolism within the tumor microenvironment (TME) by impairing the ketogenic response, further exacerbating metabolic disturbances." (PMID 40427188, 2025). "The standard chemotherapy for CRC, consisting of oxaliplatin and 5-fluorouracil, induced the polarization of macrophages to a pro-inflammatory phenotype in this model, increasing the mRNA for inflammatory cytokines, such as IL1β1, IL6, and TNFa, and increasing the phagocytosis of tumor cells." (PMID 40136707, 2025). "Those with low IL6R expression exhibited less mature myeloid cell infiltration and better overall survival (OS), whereas those with high IL6 levels, high IL6R expression, and high infiltration of tumor-associated CD163+ myeloid cells were associated with poor clinical outcomes." (PMID 40427188, 2025). "We and others have shown predominant roles of IL-6 and prostaglandins, derived from tumor-derived supernatants, or sialylation of tumor cells, in skewing monocyte differentiation away from a DC phenotype to an M2-macrophage-like state with pro-tumoral and immune suppressive features." (PMID 41086813, 2025). "Furthermore, IL-6 can exert extrinsic effects on other cells in the complex TME to maintain a pro-tumor milieu by increasing angiogenesis and tumor immunity evasion." (PMID 40933989, 2025). "Tumor stem cells release the IL-6, a pro-aging factor that induces macrophage senescenc." (PMID 41200171, 2025). "Moreover, in this model, the levels of IL-1Ra (a member of both the IL-1 and IL-6 pathways) in the tumor increased (P = 0.001) at 4 hours after incision compared with untreated TCs." (PMID 40331601, 2025). "In addition, IL-6 autocrine increases the motogenic activity of tumor cells by binding to the receptor for IL-6 on the surface of tumor cells and increases the secretion of HGF, which promotes metastasis." (PMID 41007818, 2025). "The Gene Set Enrichment Analysis (GSEA) of the RNA-seq dataset showed that the expression of many molecules related to IL6-JAK-STAT3 signaling were highly upregulated in GA muscle of KPC tumor-bearing Xbp1fl/fl mice compared to control Xbp1fl/fl mice without tumor." (PMID 40655023, 2025). "IL6 is a so-called pleiotropic cytokine with both tumor-promoting and tumor-inhibiting effects." (PMID 40043049, 2025). "In addition, ATR-I ameliorates tumor cachexia by inhibiting the biogenesis of IL-6 and extracellular vesicles derived from tumor cells." (PMID 40087774, 2025). "Therefore, the reduced expression of IL6 in PBMCs isolated from CRC patients indicates an immunosuppressive environment created by the tumor allowing tumors to evade immune detection." (PMID 40484866, 2025). "Furthermore, hesperidin significantly decreased the expression of pro-inflammatory cytokines such as TNF-alpha and IL-6 by inhibiting the pathway, thereby modulating inflammation within the tumor microenvironment." (PMID 41226277, 2025). "In breast cancer, IL-6 is often upregulated in response to tumor cells and inflammatory signals." (PMID 40486614, 2025).